NEUROD1 (neuronal differentiation 1)
Diseases named in the same sentence as NEUROD1 in open-access papers (continued):
Sharing a sentence is not in itself a finding about the gene and the disease.
cancer (33 papers, 2014 to 2026). A tumor composed of atypical neoplastic, often pleomorphic cells that invade other tissues. "This indicates that NeuroD1 has the potential to transform cancer cells from a malignant to a benign biological." (PMID 41225636, 2025). "Further studies are required to elucidate the regulatory mechanisms underlying the mutual repression of ASCL1 and NEUROD1 along with the direct NEUROD1-mediated repression of BCL2 across different types of cancer and disease." (PMID 40082639, 2025). "A growing body of work has shown the association of the SNAIL, Neuronal Differentiation 1 (NEUROD1) and Hepatocyte nuclear factor 4 (HNF4) genes with cancer." (PMID 37798384, 2023). "Based on in situ immunostaining patterns for achaete-scute homolog 1 (ASCL1) and NEUROD1, it is proposed that N-Myc-driven cancer cells emerge among ASCL1-positive precursor cells, and these early-staged cancer cells initially exhibit classic morphology." (PMID 30053872, 2018). "Based on in situ immunostaining patterns for achaete-scute homolog 1 (ASCL1) and NEUROD1, it is proposed that c-Myc-driven cancer cells emerge among ASCL1-positive precursor cells, and these early-staged cancer cells initially exhibit classic morphology." (PMID 30477547, 2018). "Neurod1 has been shown to have increased methylation levels in a variety of cancers, while variation in the gene locus methylation state has been observed in human brain." (PMID 26834554, 2015). "However, the molecular fundaments of ASCL1- and NEUROD1-regulated subtypes in both cancers remain largely unknown." (PMID 34145257, 2021). "By focusing on the NeuroD1/GPX4 axis, the study clarified the fundamental mechanism of ferroptosis in cancer cells and provided an achievable new strategy for future treatments." (PMID 41439136, 2026). "We conducted a coexpression analysis of PGC-1α against the four SCNC lineage markers—ASCL1, POU2F3, NEUROD1, and YAP1—across all 1,466 human cancer cell lines from the Cancer Cell Line Encyclopedia (CCLE)." (PMID 39589879, 2024). "Since modulating the expression of these genes is important for cancer therapy, we examined the possibility of downregulating SNAIL expression and upregulating NEUROD1 and HNF4 expression in a hypoxia-dependent manner using Cas9/dCas9 gene regulators." (PMID 37798384, 2023). "We found that the cancer subtype markers (GRP, CHGB, NEUROD1, and CHGA for NET; KRT5, DSC3, KRT6B, TP63, and KRT6A for SCC; and NKX2-1, KRT7, NAPSA, and MUC1 for ADC) were specifically expressed in the corresponding cancer subtypes." (PMID 35962452, 2022). "First, we downloaded the bulk expression data for 50 SCLC cell lines from the Cancer Cell Line Encyclopedia (CCLE) and categorized them according to the key TFs ASCL1, NEUROD1, POU2F3 and YAP1." (PMID 36195615, 2022). "Exploiting the transcriptional dependency of cancer cells (here mainly directed by two well‐known DNA‐binding proteins: ASCL1 and NEUROD1) as an Achilles’s heel to thwart their own tumorigenic potential, represents a key actionable mechanism against SCLC." (PMID 35263037, 2022). "ChIP-seq data on human cancer cell lines comparing ASCL1 and NEUROD1 transcriptional targets demonstrates that these two bHLH genes bind to distinct genomic regions." (PMID 34782629, 2021). "constructs a novel model of SCLC subtypes defined by differential expression of four key transcription regulators: ASCL1, NeuroD1, YAP1, and POU2F3 according to SCLC primary human tumors, patient-derived xenografts, cancer cell lines, and genetically engineered mouse models." (PMID 40433367, 2025). "In addition to subtype markers (ASCL1, NEUROD1, POU2F3, and YAP1), the expression of nine cancer-specific proteins was evaluated." (PMID 40107154, 2025). "Thus, four distinct subtypes of SCLC defined by the predominant transcriptional regulatory mechanism operating in cancer cells have been described on the basis of the expression of ASCL1, NEUROD1, YAP1, and POU2F346." (PMID 41290592, 2025).
cancer (continued). "Moreover, reduced EZH2 led to significantly reduced binding of LSD1, HDAC1, and DNMT1 to promoter regions of CDH1, CDKN1A, NEUROD1, and TUBB3, in agreement with increased transcription of these genes in cancer cells after EZH2 knockdown." (PMID 31130994, 2019). "In line, Gene Ontology and KEGG pathway analysis of ASCL1‐target genes and NEUROD1‐target genes in our RNA‐seq dataset showed that ASCL1 and NEUROD1 are involved in DNA metabolic process mainly devoted to RNAPII transcription regulation and cancer‐related pathways (Fig EV4A and B)." (PMID 35263037, 2022).
infection (22 papers, 2008 to 2025). The state of being infected such as from the introduction of a foreign agent such as serum, vaccine, antigenic substance or organism. "The next day after infection, the medium was switched to neuronal induction medium, and NeuroD1-infected cells exhibited bipolar processes on day 7 post-infection." (PMID 39014391, 2024). "This theory was proven in vitro, when after the infection of human astrocytes by GFAP of:NeuroD1-IRES-GFP retrovirus, NeuroD1-positive cells also express positivity for NeuN, a marker of functional neurons." (PMID 38481632, 2024). "Since we have previously shown that NR-astrocytes are hardly reprogrammed into neurons by single infection with NeuroD1-virus, we attempted to increase the NeuroD1 expression level by performing multiple infections with the viruses in this study." (PMID 36289433, 2022). "Quantified data found that 99% of GFAP::GFP infected cells were GFAP+ astrocytes, but 52.6% of NeuroD1-GFP infected cells already became NeuN+ within 1 month of infection." (PMID 33224952, 2020). "Immunostaining confirmed these qRT-PCR findings and demonstrated that only RFP+ cells produced by Ad-RFP-Neurog3 infection were immunostained with antibodies recognizing NEUROD1, NKX2.2, CHGA, SST or GHRL." (PMID 24252877, 2013). "In conclusion, our findings demonstrated that genetic manipulation producing infection by a combination of PDX-1 NeuroD1, and MafA and their subsequent expression significantly promoted insulin-producing function of mMSCs." (PMID 22761608, 2012). "Indeed, using a lentivirus infection system, mouse microglia were successfully reprogrammed into neurons by NeuroD1 overexpression, and this process tightly depends on the NeuroD1 expression level." (PMID 38667322, 2024). "Infection of adult and human duct cells with adenoviral vectors may bypass these issues by expressing Pdx1, Ngn3, neurogenic differentiation 1 (NeuroD1) or Pax4, which have also been shown to induce insulin gene expression." (PMID 36139388, 2022). "In addition, elevating the expression of NeuroD1 by the repeated infections dramatically promoted astrocyte-to-neuron (AtN) conversion at 7 dpt compared to the single infection." (PMID 36289433, 2022). "Next, NR-astrocytes were infected once (× 1) or three times (× 3) with the set of the three viruses (EGFP-, M2rtta-, and NeuroD1-viruses), and we found that the repeated infection increased both NeuroD1 and EGFP protein expression levels at the single-cell level." (PMID 36289433, 2022). "However, 6 weeks post-infection, in the “ET-1+NeuroD1 vs. ET-1+Control” group, the tuning curve width was 17.504 degrees for the ET-1+NeuroD1 hemisphere, sharper than 22.880 degrees for the ET-1+Control hemisphere (bottom)." (PMID 34490268, 2021). "Together, these results suggest that ectopic expression of NeuroD1 in reactive astrocytes significantly attenuated their reactive and neuroinflammatory properties, and such beneficial effects occurred as early as 3 days after NeuroD1 infection." (PMID 33250718, 2020). "Interestingly, Math6 mRNA expression declined 48 h post-infection, whereas levels of other Neurog3-induced mRNAs were maintained (Pax4, NeuroD1) or remained elevated (somatostatin) through 72 h." (PMID 18560595, 2008). "At 3days after infection, selective increases in the mRNA levels of insulin I (Ins1) and insulin II (Ins2) were observed in the cells that had been infected with a triple combination of adenovirus (Pdx1 and MafA, with either Ngn3 or NeuroD1) in a semiquantitative RT-PCR analysis." (PMID 29768476, 2018). "On day14 post-infection, immunostaining with astrocytic (GFAP) or neuronal (MAP2 and TUJ1) markers showed that NeuroD1-infected cells displayed decreased GFAP signal (91.6 ± 2.5% → 48.3 ± 1.4%) and exhibited neuronal morphology in both GFAP + and GFAP − cells." (PMID 39014391, 2024).
infection (continued). "The quantitative analysis found that at 3 days post-NeuroD1-mCherry viral injection (3 dpi), 92.1 ± 3.1% of NeuroD1-mCherry infected cells were GFAP-positive, indicating preferential infection of astroglial population guided by GFAP::Cre viruses." (PMID 33250718, 2020). "Viral injection at 10 days post-contusion resulted in many GFP+ cells surrounding the injury core in both control GFP and NeuroD1-GFP groups, indicating good infection rate and survival of the AAV-infected cells in the contusive SCI model." (PMID 33425896, 2020). "Math6 mRNA was expressed at low levels in untreated mPAC cells and was induced 12 h after infection with AdCMV-NEUROG3, concomitantly with appearance of Pax4 mRNA and prior to induction of NeuroD1 mRNA, two known direct targets of Neurog3." (PMID 18560595, 2008). "Conversely, expression levels of ectodermal (Pax6, Gfap, Neurod1, and Olig1) or mesendoderm (Flk1, Eomes, Hnf1b, and Mixl1) markers either not enhanced or only weakly increased after Cre infection." (PMID 40216251, 2025). "Actually, infecting cells twice (× 2) with the three viruses including NeuroD1 also increased MtN reprogramming efficiency compared to the single (× 1) infection, without further affecting cell survival." (PMID 36289433, 2022). "Different from A1 astrocyte genes, the A2 reactive astrocyte genes were not changed despite a decrease of GFAP expression after NeuroD1-infection." (PMID 33250718, 2020). "The ratios of nGFP-positive cells at 24 hours after infection with the indicated vector at an optimal multiplicity of infection (MOI) were as follows: 94.1% ± 4.5% for pAd-Pdx1; 88.8% ± 7.6% for pAd-Ngn3; 88.6% ± 3.1% for pAd-NeuroD1; and 87.7% ± 4.2% for pAd-MafA." (PMID 29768476, 2018). "Lentiviruses expressing NeuroD1 shRNAs significantly suppressed the expression of NeuroD1: by 80 % at the mRNA level and by 50 % at the protein level after 72 h infection compared to lentivirus expressing non-targeting shRNA." (PMID 26956881, 2016). "While in the “ET-1+NeuroD1 vs. ACSF+Control” group, the cumulative distribution of 1-CV of the ET-1+NeuroD1 hemisphere was left-shifted compared to the ACSF+Control hemisphere at 3 weeks but was not different at 6 weeks post-infection." (PMID 34490268, 2021).
brain diseases (1 paper, 2023). "NeuroD1 treatment has been suggested to promote neurofunctional recovery in several brain diseases, although the mechanisms remained debatable." (PMID 37953259, 2023).
NEUROD1 also shares sentences with these, for which no sentence is quoted: neurological disorders (4 papers); carcinoids (2); colorectal (2); Insulin resistance (2); retinitis pigmentosa (2); acute myeloid leukemia (1); adenocarcinoma (1); Anxiety (1); astrocytoma (1); autism spectrum disorder (1); Autoimmunity (1); bacterial infections (1); Bardet-Biedl syndrome (1); cardiomyopathy (1); clear-cell renal cell carcinoma (1); corticotropinomas (1); deafness (1); depression (1); diabetic neuropathy (1); diffuse astrocytoma (1); diffuse large B-cell lymphoma (1); gastric cancer (1); hearing loss (1); hypopituitarism (1); hypothyroidism (1); immune dysfunction (1); insomnia (1); IPEX syndrome (1); kidney (1); kidney disease (1).
A further 24 diseases each share a sentence with NEUROD1 in 1 paper.